HIF1A (hypoxia inducible factor 1 subunit alpha)
Diseases named in the same sentence as HIF1A in open-access papers (continued):
Sharing a sentence is not in itself a finding about the gene and the disease.
renal fibrosis (102 papers, 2013 to 2026). A final common manifestation of a wide variety of chronic kidney diseases characterized by glomerulosclerosis and tubulointerstitial fibrosis. "CD248 is also identified as a pivotal stromal cell marker in renal allograft rejection, associated with HIF-1α and IL-1β pathways (also two pivotal pathways in renal fibrosis of DN)." (PMID 41382249, 2025). "P21 is thought to be the critical mediator of cell cycle arrest in renal fibrosis, and its activation was found to be associated with the induction of HIF-1α." (PMID 37446141, 2023). "Hif-1α and NF-kB crosstalk is involved in many hypoxia-associated diseases, such as ischemic stroke, obstructive sleep apnea, and renal fibrosis." (PMID 36675720, 2022). "However, endothelial HIF-1α is essential in initiating glomerular injury and progression to renal fibrosis by the transcriptional activation of genes encoding multiple vasoactive proteins." (PMID 28448446, 2017). "We found that DKD development and progression to renal fibrosis entailed profound changes in proximal tubule metabolism, characterized by a switch from fatty acid utilization to glycolysis and lipid accumulation, which is associated with the increased expression of HIF-1α." (PMID 32444604, 2020). "In addition, in angiotensin II infusion model of hypertensive chronic kidney disease, HIF-1α has been shown to be essential to initiate the glomerular injury and progression to renal fibrosis by transcriptional activation of genes encoding multiple vasoactive proteins." (PMID 28468297, 2017). "ZGP and YGP inhibited renal fibrosis and relieved the decrease in glucose consumption through transcriptional regulatory network of HIF1A and PPARA." (PMID 40417738, 2025). "Empirical studies have demonstrated that zinc supplementation can mitigate pathological angiogenesis and ameliorate renal fibrosis through the inhibition of the HIF-1α/VEGF signaling pathway." (PMID 39995420, 2025). "The preceding discussion has elucidated the role of HIF-1α in facilitating the advancement of renal fibrosis through multiple mechanisms." (PMID 39995420, 2025). "In this study, we found that ZGP, YGP, and its components activated the transcriptional regulatory networks of HIF1A, as well as the downstream genes PDK1 and CA9, which were closely associated with renal fibrosis and ECM degradation." (PMID 40417738, 2025). "Our next step will be to target the HIF-1a/PDK 1 axis to investigate how yaks are protected from renal fibrosis in a hypoxic environment, to provide a physiological for revealing the hypoxic adaptation of yak kidneys." (PMID 39518833, 2024). "HIF-1α promotes renal fibrosis, perpetuating a cycle of inflammation and fibrosis in the diabetic kidneys." (PMID 39033184, 2024). "Hypoxia-inducible factor-1 α (HIF-1α) is an important transcription factor that senses the oxygen status, induces adaptive changes in cellular metabolism, and plays an important role in renal fibrosis and glucose metabolism." (PMID 39518833, 2024). "Our findings indicate that ANGPTL4 is a key regulatory factor in renal fibrosis, forming a loop with HIF-1α, potentially serving as a novel therapeutic target for RIF." (PMID 38992710, 2024). "According to previous studies, the inactivation of PKM2 leads to abnormal glycolysis through the activation of HIF-1α, which contributes to renal fibrosis." (PMID 37007793, 2023). "EGFR activation mediates HIF-1α activation and subsequent the induction of aberrant glycolysis, which finally promoting renal fibrosis in DKD." (PMID 36874012, 2023). "PKM2, the crucial critical enzyme in glycolysis, and PKM2 insufficiency result in aberrant glycolysis by activating HIF-1α, which contributes to the pathophysiology of renal fibrosis." (PMID 37007793, 2023). "Our study indicates that HIF1α plays a significant role in the effect of PFKFB3-medaited glycolysis on phenotypic alterations observed in macrophages in renal fibrosis." (PMID 38035106, 2023).
renal fibrosis (continued). "Activation of tetrameric PKM2 formation can reduce the entry of PKM2 dimer form into the nuclear and activation of HIF-1α, alleviate abnormal glycolysis and renal fibrosis, and play a role in renal protection." (PMID 36874012, 2023). "Mechanistic studies indicate that glycolytic metabolites stabilize HIF1α, leading to alterations in macrophage phenotype that contribute to renal fibrosis." (PMID 38035106, 2023). "HIF-1α is deemed to be a major mediator of the hypoxic response and plays a key role in the development of renal fibrosis in mice." (PMID 37626956, 2023). "For example, Kimura and colleagues found that injection of a pharmacologic HIF1α inhibitor decreased renal fibrosis in unilateral ureteral obstruction model." (PMID 35966094, 2022). "Hypoxia-inducible factor-1 α (HIF-1α), a vital transcription factor, senses oxygen status, induces adaptive changes in cell metabolism, and plays an important role in renal fibrosis and glucose metabolism." (PMID 35957825, 2022). "In another study on hypertensive DN kidneys of mice with renal fibrosis, the upregulation of HIF-1α was found." (PMID 36142323, 2022). "Studies suggest that activation of HIF1α signaling pathways play a pivotal role in renal fibrosis in various kidney diseases." (PMID 35966094, 2022). "Renal hypoxia induced factor 1α (HIF1α) is critical in the development of glomerulosclerosis and renal fibrosis." (PMID 35966094, 2022). "In this review, we summarized the latest knowledge on the mechanisms of action and function of HIF-1α in regulating glucose metabolism reprogramming during renal fibrosis, focusing on the regulation of glycolysis-related enzymes." (PMID 35957825, 2022). "In the kidney, the HIF-1α signalling pathway is believed to play a role in the early onset of renal fibrosis." (PMID 33639908, 2021). "Several evidences have already shown that HIF-1α is a central regulator of renal fibrosis in different pathological conditions." (PMID 34925478, 2021). "For example, it has been shown that overexpression of HIF1α promotes and inhibition of it attenuates the progression of renal fibrosis in kidney disease models." (PMID 34867480, 2021). "A recent study showed that HIF1α deletion facilitated adipose stem cell-mediated repair of renal fibrosis in diabetic mice." (PMID 32248837, 2020). "Aside from hypoxia, glucose overload, angiotensin II, and albuminuria also promote renal fibrosis by stabilizing HIF1α." (PMID 32364526, 2020). "Other studies have shown that overexpression of HIF-1α in tubular epithelial cells contributes to the progression of renal fibrosis, and the inhibition of HIF-1α expression prevents the progression of renal fibrosis and attenuated DN progression." (PMID 33203103, 2020). "Some studies have shown that the increase in HIF-1α expressions and the development of renal fibrosis are related to the activation of the Wnt/β-catein signaling pathway, which is caused by podocyte dysfunction and promotes the formation of proteinuria." (PMID 31354858, 2019). "A later study further demonstrated that inhibiting HIF-1α by siRNA during reperfusion had deleterious effects on kidney injury and renal fibrosis by downregulating miR-127-3p and inducing its target gene Bcl6." (PMID 30823476, 2019). "Of particular interest, TMZ inhibited delayed renal fibrosis through upregulation of HIF-1α in pigs after I/R injury." (PMID 30057668, 2018). "Consistently, elevated epithelial HIF-1α levels exacerbate the progression of kidney damage and renal fibrosis in a rat model of hypertension induced by high-salt diet and nitric oxide withdrawal." (PMID 28468297, 2017). "Accumulating evidence show that HIF, especially HIF-1α, is a key regulator of renal fibrosis under various pathological conditions." (PMID 28468297, 2017). "Genetic inactivation of the Vhlh gene in tubular epithelial cells resulted in constitutive HIF-1α stabilization and accelerated renal fibrosis." (PMID 28774305, 2017).
renal fibrosis (continued). "Hif-1α was recently demonstrated to be involved in tissue fibrosis and influenced by Ang II 16,17, such as in vascular and renal fibrosis." (PMID 25823960, 2015). "Additionally, YC-1, a selective inhibitor of HIF-1α, has been found to significantly improve renal function and mitigate pathological injury in diabetic mice, as well as reduce the severity of renal fibrosis." (PMID 39995420, 2025). "Similarly, the combination of Astragalus membranaceus and Panax notoginseng synergistically alleviates renal fibrosis via the HIF-1α/JAK2/STAT3 axis." (PMID 41487503, 2025). "However, in some studies, elevated HIF-1α showed benefits, and pretreatment of roxadustat reduced renal fibrosis through the Akt/GSK-3β/Nrf2 pathway." (PMID 40040789, 2025). "In addition, previous studies have shown that increased expression of HIF-1α in diabetic kidneys contributed to renal fibrosis and the progression of DN." (PMID 39033184, 2024). "Research indicates involvement of SIRT1/HIF-1α in renal fibrosis." (PMID 39335456, 2024). "Our study also implicates that PFKFB3 may act as a bridge to mediate the crosstalk of TGF-β1 and HIF-1α signaling pathways in renal fibrosis." (PMID 38035106, 2023). "All these results suggest that PKM2 inactivation by acrolein may contribute to renal fibrosis via HIF1α accumulation and induction of the EMT program and abnormal glycolysis." (PMID 37007793, 2023). "Notably, the hypoxia-inducible TF Hif1a, a key regulator for renal fibrosis under various conditions was also upregulated in the EPT, PCT and CNT." (PMID 37727504, 2023). "Among these protein targets, pyruvate kinase M2 (PKM2) was found to be modified by acrolein at Cys358, leading to the inactivation of PKM2 contributing to the pathogenesis of renal fibrosis through HIF1α accumulation, aberrant glycolysis, and upregulation of EMT in HFD-STZ-induced DN mice." (PMID 37007793, 2023). "Moreover, knockout of endothelial PHD2 suppressed the expression of AT1R and prevented Ang‐II‐induced upregulation of HIF‐1α/2α and renal fibrosis and injury." (PMID 35441828, 2022). "A series of studies have confirmed that the expression of HIF-1α increases in renal fibrosis, suggesting that HIF-1α may play a vital role in promoting renal fibrosis." (PMID 35957825, 2022). "Through cell transfection and other experiments, previous studies have shown that the HIF-1α/KIM1 signaling pathway can participate in the process of renal fibrosis in diabetic nephropathy by regulating the KIM1 expression in renal tubular epithelial cells under a high-glucose environment." (PMID 36141135, 2022). "Conversely, experimental knockout or inhibition of HIF-1α attenuates renal fibrosis." (PMID 35721758, 2022). "Under hyperglycemic conditions, elevated expression of HIF-1α, a transcriptional factor mediating hypoxia adaptation, could stimulate renal fibrosis and proteinuria." (PMID 35721758, 2022). "We previously demonstrated that Twist1 is involved in hypoxia-induced EMT and contributes to fibrogenesis in renal tubular cells by HIF-1α activation, but it was still unclear whether downstream molecules regulated by Twist1 could promote renal fibrosis." (PMID 35182235, 2022). "Moreover, HSA promoted macrophage glycolysis through tubular epithelial cell-derived EVs by stabilizing HIF-1α, thus inducing renal fibrosis and inflammation." (PMID 35962319, 2022). "In summary, targeting metabolic pathways, especially HIF-1α-mediated aerobic glycolysis, may be beneficial in renal fibrosis." (PMID 35957825, 2022). "Specifically, HIF-1α could bind to Smad3, upregulate the level of fibrosis-related proteins, and promote renal fibrosis." (PMID 35957825, 2022). "Recent evidence indicates that signal transducer and activator of transcription 3 (STAT3) might mediate the process of renal fibrosis, which could induce the expression of hypoxia-inducible factor-1α (HIF-1α)." (PMID 34193173, 2021).
renal fibrosis (continued). "HIF-1α is considered to be a key transcription factor in renal fibrosis induced by hypoxia." (PMID 34211565, 2021). "The experimental validation results demonstrated that NE-THCQ might inhibit the inflammatory processes, reduce ECM deposition and reverse EMT via PI3K/AKT/mTOR and HIF-1α/VEGF signaling pathways to exert its effect against renal fibrosis." (PMID 32372953, 2020). "On the other hand, a dysregulated and continued activation of HIF-1α promotes renal fibrosis." (PMID 33202532, 2020). "Therefore, we investigated the role of the HIF-1α/VEGF signaling in the pathogenesis of NE-THCQ against renal fibrosis." (PMID 32372953, 2020). "We hypothesized that modulation of hypoxia and HIF-1α by UCP2 regulates renal fibrosis through promoting lipid and ECM accumulation." (PMID 31932578, 2020). "However, the role of HIF-1α in the renal fibrosis and extracellular matrix (ECM) accumulation has been conflicting." (PMID 32884936, 2020). "Via the miR-34a-5p/sirtuin 1 (SIRT1)/HIF-1α pathway, long intergenic noncoding RNA (lincRNA) 1700020I14Rik suppresses expression of renal fibrosis biomarkers, inhibits mesangial cell proliferation under diabetic conditions, and is involved in progression of DN." (PMID 33299464, 2020). "Since Bnip3 is a well‐known player of hypoxia‐induced apoptosis and Snail and TGF‐β1 are the key regulators of epithelial to mesenchymal transition and renal fibrosis, the activation of HIF‐1α‐regulated pathways could mediate renal damage." (PMID 30614190, 2019). "To clarify whether the effect of 1700020I14Rik on renal fibrosis was the interaction with miR-34a-5p through Sirt1/ HIF-1α pathway, we firstly identified the effect of 1700020I14Rik on the expressions of Sirt1 and HIF-1α." (PMID 29700282, 2018). "However, in cells cultured in hypoxia + PP1, compared with cells cultured only in hypoxia, the protein level of HIF-1α decreased; studies have shown that decreased HIF-1α can alleviate renal fibrosis." (PMID 29462885, 2018). "However, in a rat remnant kidney model by removal two-thirds of the left kidney to induce renal fibrosis, treatment with L-mimosiney to activate HIF-1α can attenuate renal tubulointerstitial fibrosis." (PMID 28468297, 2017). "In renal fibrosis, Bim1 mediated the regulatory role of HIF‐1α in EMT in tubular epithelial cells." (PMID 26781174, 2016). "Additionally, it was confirmed that HIF-1α promotes renal fibrosis through activating angiotensin II in vivo and in vitro experiments." (PMID 27069929, 2016). "Notably, this hypoxic state triggers hypoxia-inducible factor-1α (HIF-1α) activation, which subsequently upregulates the Wnt/β-catenin pathway to promote renal fibrosis through epithelial-mesenchymal transition (EMT) in tubular cells and interstitial fibroblast activation." (PMID 40470049, 2025). "Additionally, therapeutic ultrasound has anti-fibrotic effects in reducing renal fibrosis on experimental hypertensive nephropathy and diabetic nephropathy in mice and in reducing the density of collagen type I, HIF-1α, and α-SMA after prolonged hypoxia-induced cardiac fibrosis in mice." (PMID 38668425, 2024). "Likewise, we observed accumulation of HIF1α protein associated with enhanced TGF-β and CTGF expression in HFD-LL rats which may explain the aggravation of renal fibrosis as a result." (PMID 35966094, 2022). "Besides, HIF-1α is associated with activating fibrotic genes such as α-SMA and fibroblast-specific protein-1 (FSP-1), resulting in an EMT process and eventually leading to renal fibrosis." (PMID 35855831, 2022).
renal fibrosis (continued). "Our study indicated that the process of ferroptosis might aggravate albuminuria, damage renal tubules, and enhance renal fibrosis in diabetic models through HIF-1α/HO-1 pathway, which may contribute to the further study on the pathogenesis of DN and provide a therapeutic target for DN." (PMID 33679620, 2021). "However, whether ferroptosis-induced-renal fibrosis is regulated by HIF-1α/HO-1 pathway has been unclear." (PMID 33679620, 2021). "Hypoxia-inducible factor (HIF-1α) and Lysyl oxidases (LOXs) are responsible for the increased EMT and ablation of HIF-1α and inhibition of LOXs could ameliorate renal fibrosis, making LOXs and HIF-1α possible targets for an anti-EMT and anti-fibrosis therapy in kidney." (PMID 33409282, 2020). "The expression of HIF1a, a transcription factor stabilized by poor oxygen delivery, was also elevated in grafts, suggesting a hypoxic milieu that may be partially explained by renal fibrosis." (PMID 28704481, 2017). "Furthermore, recent evidence shows that NPs might induce renal fibrosis through a ROS- mediated HIF-1α signaling pathway." (PMID 27678081, 2016). "ZGP and YGP mediated HIF1A networks and downstream genes of CA9 and PDK1 in TGFβ‐induced HK2 cells for improving renal fibrosis." (PMID 40417738, 2025). "Previous research has indicated that elevated levels of HIF-1α can enhance the expression of the downstream target gene VEGF, potentially resulting in pathological angiogenesis and subsequent renal fibrosis." (PMID 39995420, 2025). "An active component of Licorice, licochalcone A, inhibits HIF-1α, TGF-β1 and AGEs, thereby ameliorating renal fibrosis in STZ-induced type 2 diabetic mice." (PMID 41459479, 2025). "Under hypoxic conditions, HIF-1α translocates to the nucleus, regulates downstream proteins, promotes ECM deposition, and accelerates renal fibrosis progression." (PMID 41459479, 2025). "In tethered cells, high glucose levels increase the expression of HIF‐1α and its target gene ADAM17, thereby accelerating renal fibrosis." (PMID 40977522, 2025). "SIRT1 modulates inflammation through various signaling pathways, including NF-κB, HIF-1α, HMGB1, PPAR, and AMPK, which play crucial roles in the pathogenesis of renal fibrosis." (PMID 39335456, 2024). "Studies have demonstrated that HIF-1α promotes aberrant glycolysis, which finally leading to ECM accumulation and renal fibrosis in mouse models of chronic/hypoxic renal injury models." (PMID 36874012, 2023). "In renal fibrosis, when PP1 is used to inhibit Src activation, it can reduce HIF-1α expression, which is one of the important mechanisms to alleviate renal fibrosis." (PMID 38077794, 2023). "Nevertheless, administration of butyrate blotted renal fibrosis and restored renal function by suppressing SDF-1-induced inflammation and TGF-β as well as improving HIF-1α." (PMID 37789355, 2023). "In HFD-STZ-induced DN mice, HIF-1α accumulation, an increase in the EMT program, and an elevation of the renal fibrosis markers fibronectin, collagen 1, and α-SMA were all consistently observed." (PMID 37007793, 2023). "The overall results indicated that ARAP1 inhibition was highly effective in limiting renal fibrosis and aberrant glycolysis by reducing the PKM2 dimer expression and subsequent HIF-1α nucleus accumulation and activation in diabetic mice." (PMID 36874012, 2023). "EGFR activation has been reported to participate in the activation of HIF-1α by promoting dimer PKM2 expression and enter nucleus, eventually leading to ECM accumulation and renal fibrosis in DKD." (PMID 36874012, 2023). "Studies have shown that activating the PI3K/Akt/mTOR and HIF-1α signaling pathways can effectively inhibit inflammatory reactions, reduce ECM deposition, and reverse EMT, and thus play a protective role in renal fibrosis." (PMID 35957825, 2022). "The expression of hypoxia-inducible factor-1α (HIF-1α), Beclin-1, and LC3 were significantly increased in UUO-induced renal fibrosis." (PMID 35897713, 2022).